INS (insulin)
Diseases named in the same sentence as INS in open-access papers (continued):
Sharing a sentence is not in itself a finding about the gene and the disease.
coronary artery disease (continued). "Elevated IL-6 concentrations have been linked to multiple clinical parameters (e.g., blood pressure, insulin sensitivity and coronary artery disease)." (PMID 35352134, 2022). "Such difference was consistently observed in subgroup analyses stratifying for insulin usage or known coronary heart disease." (PMID 36102222, 2022). "However, a doubtful reduction of coronary artery disease by glucose-lowering treatment was found in large meta-analyses, possibly because the benefits were partly counterweighed by an increased occurrence of severe hypoglycaemic episodes, associated with the intensive insulin therapy." (PMID 36030229, 2022). "Despite the advent of insulin and exercise and dietary management largely controlling the progression of T2DM, comorbidities associated with the disorder, especially coronary artery disease (CAD), are still an important cause of death." (PMID 35842724, 2022). "These vascular cell adhesion molecules respond to inflammatory cytokines and initiate the pathologic process of coronary artery disease and insulin resistance by forming atherosclerotic plaque and inhibiting insulin sensitivity and other biological functions." (PMID 34616762, 2021). "In conclusion, this study shows that younger age, insulin use and ischemic heart disease are impacting factors of HbA1C variability, and support our assumption that diabetic patients with higher HbA1C variability have different characteristics as a group." (PMID 34537062, 2021). "The results of a clinical trial conducted on patients with coronary artery disease showed that after replacing refined rice with legume powder and whole grain products, as a source of carbohydrates, glucose and insulin concentrations changed significantly." (PMID 32429894, 2020). "A randomized double-blind placebo-controlled clinical trial revealed that FO supplementation significantly improved levels of gene expression related to insulin, lipid and inflammation in diabetic patients with coronary heart disease." (PMID 32028957, 2020). "Other baseline characteristics, including previous ischemic heart disease, the prescription of insulin and the clinical presentation at the time of the index PCI did mostly not differ between the groups." (PMID 33008407, 2020). "Similar proportions of individuals in the alirocumab and usual care groups had ASCVD (defined as coronary heart disease, peripheral arterial disease, or ischemic stroke; 36.7% vs 41.4%) and were receiving insulin (40.6% vs 44.8%) at baseline." (PMID 32035487, 2020). "In patients on insulin, the presence of multivessel coronary disease and left main disease was especially high (64% compared to 6.3% for non-diabetics)." (PMID 32781780, 2020). "In adult studies, LV diastolic dysfunction can be attributed to cardiomyocyte apoptosis, coronary artery disease, chronic inflammation, and insulin resistance." (PMID 31120986, 2019). "The ability of four fasting insulin resistance indexes to predict long-term coronary heart disease, cox regressions in 1049 male subjects aged 71 years, 135 events during median 8 years of follow-up." (PMID 31694444, 2019). "Linoleic acid, as ω-6 PUFA, decreases the levels of total plasma cholesterol, has favorable effects on the prevention of coronary heart diseases and cancers, and increases insulin sensitivity." (PMID 29853958, 2018). "Since all type 2 diabetic patients are insulin resistant, it is difficult to assess its role in the development of coronary artery disease of diabetics." (PMID 29732028, 2018). "This was reduced slightly to 36% (HR: 1.36; 95% CI 1.15–1.62) when we adjusted for age, gender, duration of insulin use, albumin, glomerular filtration rate, lipid profile, and coronary heart disease history." (PMID 28830436, 2017). "In the elderly population of Uppsala, insulin resistance, as measured by the gold-standard method of euglycaemic insulin clamp, predicted coronary heart disease over a 10-year period." (PMID 26861377, 2016).
coronary artery disease (continued). "This phenomenon can be explained by increased cancer and also coronary heart disease mortality observed among diabetic patients treated with insulin." (PMID 27724912, 2016). "Although several studies have shown that serum insulin was negatively associated with HDL-C levels and strongly associated with ischemic heart disease, the effect of serum C-peptide levels on HDL-C concentration is unclear." (PMID 25559358, 2015). "On the other hand, the expression of adiponectin, which is an anti-inflammatory cytokine increasing the insulin sensitivity, was reduced in the epicardial adipose tissue in the patients with coronary artery disease." (PMID 25530760, 2014). "A literature search was conducted to examine the effects of canola oil consumption on coronary heart disease, insulin sensitivity, lipid peroxidation, inflammation, energy metabolism, and cancer cell growth." (PMID 23731447, 2013). "Before propensity score matching, ARB users were more likely to have thyroid disease, kidney disease, proteinuria and use insulin, and less likely to have ischemic heart disease, gout, use gout drugs and use H2 blockers than CCB users." (PMID 22594344, 2012). "One possible explanation, however, is that these patients are developing a reduced insulin sensitivity due to an on-going unhealthy lifestyle that also gave them coronary heart disease." (PMID 22815970, 2012). "One patient during LM50 treatment experienced pneumonia, while two patients during human insulin mix 50 treatment experienced coronary artery disease and hepatitis E respectively." (PMID 18657196, 2008). "Previous studies have reported that coronary artery disease can be associated with impaired β-cell secretory capacity independent of insulin sensitivity." (PMID 41375645, 2025). "Adjusted for insulin use, gender, age, ischemic heart disease, BMI ≥ 30, smoking." (PMID 41282290, 2025). "The role of triglyceride-glucose (TyG) index, an insulin resistance indicator, in glycemic management for diabetic patients with coronary artery disease (CAD) was still unknown." (PMID 38184572, 2024). "Coronary artery disease is often more prevalent and widespread when DM is present, and the tendency for restenosis, stent thrombosis, and graft occlusion is increased, especially in those treated with insulin." (PMID 39597855, 2024). "This suggests that enhancing insulin sensitivity may potentially contribute to mitigating coronary artery disease and improving clinical outcomes." (PMID 39027474, 2024). "Associations between cholesterol, triglycerides, ischemic heart disease (IHD), insulin, oral anti-diabetic drugs (OADs), a combination of OADs and insulin, and HbA1c levels exhibited varying degrees of correlation across all quantiles (p < 0.05), demonstrating a positive effect." (PMID 37308493, 2023). "Mediation analysis revealed that increased fasting insulin could be positioned within a pathway from short telomere length and ischemic heart disease." (PMID 36689071, 2023). "In non-pregnant status, reduced asparagine levels were associated with the incidence of DM2 and coronary artery disease (CAD) in the Malmo Preventive Project and aspartate was found among the amino acids significantly associated with reduced insulin secretion in the METSIM study." (PMID 36428943, 2022). "The effect of insulin therapy on coronary artery disease (CAD) remains controversial." (PMID 36238131, 2022). "Given our findings, metformin may contribute to its reported effect in preventing cancer and tumor progression, protecting against coronary heart diseases, and improving insulin sensitivity by lowering mid-chain HETEs, particularly 11-HETE." (PMID 36232780, 2022). "For instance, insulin sensitivity has been shown to be a marker of coronary artery disease risk in non-diabetic populations." (PMID 35129650, 2022).
coronary artery disease (continued). "Thus, we aimed to investigate relationship among insulin therapy, plasma insulin/C-peptide levels, and the morbidity of severe coronary artery disease (CAD) in T2DM." (PMID 36238131, 2022). "Similarly, lower HDL-p profiles have been reported among metabolically unhealthy subjects, subjects with coronary artery disease, impaired insulin sensitivity and increased carotid media thickness." (PMID 35918691, 2022). "Subgroup analyses were performed by concurrent use of insulin and the presence of coronary heart disease; sensitivity analysis was performed by excluding patients with either valvular heart disease or cardiomyopathy and by excluding patients with heart failure." (PMID 36102222, 2022). "We also evaluated the extent of coronary artery disease based on the number of coronary vessels significantly affected by disease (i.e. one -, two—or three-vessel coronary artery disease) in relation to the insulin resistance GRS." (PMID 34143812, 2021). "The fasting insulin level correlated negatively with carbohydrate intake in healthy Hispanic and White cohorts, normal healthy Netherlanders, and Americans with coronary artery disease." (PMID 33829033, 2021). "Retinopathy treated with laser (32 vs 11%, p = 0.003), urinary albumin/creatinine ratio >3 mg/mmol (61 vs 31%, p = 0.001), coronary arterial disease (90 vs 73%, p = 0.04) and insulin treatment (77 vs 42%, p = 0.0003) were significantly more common in patients with neuropathy." (PMID 32092076, 2020). "Likewise, oleic acid is a monounsaturated fatty acid that had been linked to a reduction in coronary heart disease due to its ability to reduce LDL-cholesterol, thrombogenicity, LDL-oxidative susceptibility as well as insulin sensitivity factors." (PMID 31055712, 2019). "The role of coronary artery disease is also well-established in the current literature, suggesting that DM and especially insulin therapy, is a strong predictor for cardiovascular mortality as well as particularly for late or repeat revascularization irrespective of an early procedure." (PMID 31138207, 2019). "The risk factors independently associated with AKI were male sex, reduced eGFR, absence of ischemic heart disease, use of ACEIs/ARBs and insulin." (PMID 28460637, 2017). "Another study which was conducted in 60 subjects of both sexes (20 males and 40 females) diagnosed with T2DM and coronary heart disease also showed beneficial effects of Se supplementation (200 μg/day for eight weeks) in terms of decreased insulin, HOMA-IR, HOMA-B parameters, and increased QUICKI." (PMID 27983572, 2016). "First-pass perfusion MRI may represent a valuable diagnostic tool for the early detection of cardiac microvascular perfusion abnormalities in obese, insulin resistant persons, and in patients with non-ischemic heart disease." (PMID 26576929, 2015). "The current study is also timely due to the recent, but still nascent findings, that alternating days of 24 hours of fasting may confer protection against coronary artery disease and improve insulin sensitivity in humans." (PMID 24454949, 2014). "In fact, it also has been shown that L-carnitine may ameliorate metabolic diseases by increasing insulin sensitivity of the skeletal muscle and may reduce ischemic heart disease." (PMID 25303894, 2014). "However, additional large-scale studies with improved experimental designs are required to further verify the role of insulin in coronary artery disease." (PMID 24669260, 2014). "And, as such, the use of chronic aspirin in T1BDM might be helpful to prevent coronary artery disease through the inhibition of dermcidin synthesis as well as through increased systemic insulin synthesis due to the stimulation of nitric oxide synthase." (PMID 24649391, 2014).
coronary artery disease (continued). "Besides weight gain, increased sugar consumption in Bahraini children is likely to decrease their HDL cholesterol, increase LDL cholesterol, triglycerides, blood glucose and insulin concentrations, factors which are related to Coronary Heart Disease mortality." (PMID 21645325, 2011). "Finally, other longitudinal blood DEGs such as Mafa [insulin gene expression in pancreatic β cells] and Mlxipl [regulates glycolysis and lipogenesis; involved in both AD and coronary artery disease] were eliminated in response to CBD in 3xTg-AD animals." (PMID 40979532, 2025). "Moreover, more than 35% of patients prescribed insulin at hospital discharge were affected by CVD (heart failure and/or ischemic heart disease), thus advocating that a careful assessment among older, frail patients should be carried out before antidiabetic treatment intensification with insulin." (PMID 36767972, 2023). "A significant association of lower DII® with lower values of insulin, HOMA-IR, triglycerides, and CMI index was observed among the CD group participants, which was similar to that reported by an Australian study evaluating the effect of a Mediterranean diet on patients with coronary heart disease." (PMID 33266499, 2020). "Collectively, these findings suggest that vascular endothelial inflammation that results from dysregulated insulin signaling (homeostasis) may contribute to coronary artery disease, and that either downregulation or upregulation of the insulin pathway may lead to inflammation of endothelial cells." (PMID 31835296, 2019). "Even if HIIT has also been proposed for patients with lifestyle-induced chronic diseases such as coronary artery disease or heart failure it may be detrimental for cardiac insulin sensitivity and blood flow capacity as shown for healthy but untrained middle-aged men." (PMID 29719514, 2018). "In the high insulin group, no significant risk of severe coronary artery disease was identified." (PMID 24669260, 2014). "The evidence suggested an increase in the risk of ischemic heart disease associated with elevated plasma FFA (top vs lowest tertile) after correction for non-lipid risk factors, although further multivariate adjustment for lipid parameters and insulin weakened the association." (PMID 24410812, 2014). "In a standardized meta-analysis we found that coronary heart disease risk increased with 46% for an increase of one standard deviation in HOMA-IR concentration compared to an increase of 21% for fasting glucose concentration and an increase of 4% for fasting insulin concentration." (PMID 23300589, 2012). "This study aims to investigate the causal relationship between intake of artificial sweeteners and coronary heart disease (CHD) and identify and quantify the role of insulin sensitivity index as a potential mediator." (PMID 41824861, 2026). "For TyG-BMI, the indirect effects of insulin-mediated total CVD and coronary heart disease were 11.4% and 29.5." (PMID 38184598, 2024). "We examined whether the addition of high-load (HL) or low loads (LL) RT has any effect on the levels of insulin resistance and lipids versus aerobic training (AT) alone in patients with coronary artery disease (CAD)." (PMID 36918949, 2023). "The relationships between serum insulin levels (both postprandial and basal) and insulin resistance of EAT adipocytes were demonstrated in patients with coronary heart disease." (PMID 36009601, 2022). "In humans, pioglitazone treatment enhances insulin-stimulated myocardial glucose uptake as measured through 18FDG PET across the whole spectrum of glucose tolerance, including T2D with coronary artery disease." (PMID 34006325, 2021). "In unadjusted data, the FDR were older, had stronger heredity for coronary heart disease, lower body mass index and weight, higher OGTT plasma glucose concentrations, and impaired insulin secretion (all p < 0.05)." (PMID 28705209, 2017).
coronary artery disease (continued). "Compared with patients without unplanned revascularization, those who experienced revascularization were more frequently male, current smokers, and insulin users, and had higher proportions of prior myocardial infarction, prior PCI, and multivessel coronary artery disease (all p < 0.05)." (PMID 41531781, 2025). "Regular exercise is an evidence-based recommendation for non-pharmacological therapy in patients with T2DM and coronary heart disease, with a focus on aerobic exercise due to its benefits on insulin sensitivity and vascular function." (PMID 40517337, 2025). "Of note, most patients included in this study were relatively healthy, with an eGFR of at least 45 mL/min/1.73 m2; no history of ischemic heart disease or heart failure; and not taking metformin, insulin, SGLT2is, ACEis, or ARBs." (PMID 39133485, 2024). "Features with significant predictive power (all p < 0.001) were subretinal fluid, FAZ eccentricity, ellipsoid zone disruption, past anti-VEGF therapy, insulin use, and no ischemic heart disease." (PMID 39797135, 2024). "Additionally, coronary artery disease (CAD) and atrial fibrillation (AF) were identified in 15 and 10 insulin users, respectively, while other ischemic heart diseases (IHD) and various cardiovascular complications occurred in 18 and 14 events, respectively." (PMID 39295783, 2024). "Furthermore, the study findings highlight the significance of cholesterol, triglyceride, ischemic heart disease (IHD), insulin, oral antidiabetic medications (OADs), and the combination of OADs plus insulin in relation to HbA1c levels." (PMID 37308493, 2023). "Ischemic heart disease was founded in 25% of patients in group without insulin and in 44 % of patients in group with insulin therapy, with statistically significant the p-value 0.008." (PMID 36983573, 2023). "Furthermore, the insulin level and HOMA-IR were significantly lower in prediabetic patients with coronary artery disease after AET intervention than in the control group." (PMID 34488728, 2021). "This variant has a positive association with coronary artery disease and a negative association with HOMA-B (a method that assesses β-cell function from basal fasting glucose and insulin)." (PMID 35096005, 2021). "In this study, an upsurge in MPV values had been observed in insulin-resistant non-obese, non-diabetic CAD (coronary artery disease) patients in comparison to insulin-sensitive non-obese, non-diabetic CAD patients." (PMID 33031385, 2020). "The insulin response to oral glucose loading has been shown to be a significant predictor of coronary artery disease in non-diabetic adults." (PMID 31590437, 2019). "The aim of this study was to evaluate insulin resistance and coronary artery disease in non-diabetic patients." (PMID 29732028, 2018). "It seems that, for example, inhibition of de novo ceramide synthesis may be beneficial to improve myocardial systolic function in ischemic heart disease, but attenuation of CERK can improve the insulin sensitivity." (PMID 26076974, 2015). "This suggests that in the process of coronary artery disease in patients with T2DM, plasma insulin may interact with the rs1324551 SNP." (PMID 24669260, 2014). "Secondly, this study examines the impact of glycated hemoglobin and insulin on the relationship between TyG, TyG-WC, TyG-WHtR, and TyG-BMI and CVD mortality, total CVD, congestive heart failure, myocardial infarction, angina pectoris, and coronary heart disease." (PMID 38184598, 2024). "Testosterone might turn out to be a key player in controlling insulin sensitivity in men.The levels of testosterone are low in men with T2DM and coronary heart diseases indicating that testosterone replacement therapy couldpotentially improve insulin sensitivity in men." (PMID 39411775, 2024).